TNFRSF1A (TNF receptor superfamily member 1A)
Diseases named in the same sentence as TNFRSF1A in open-access papers (continued):
Sharing a sentence is not in itself a finding about the gene and the disease.
metabolic syndrome (5 papers, 2017 to 2026). A cluster of metabolic risk factors for CARDIOVASCULAR DISEASES and TYPE 2 DIABETES MELLITUS. "In another study, the impact of polymorphism A36G of the TNF-alpha receptor 1 (TNFRSF1A + 36A/G) on plasma concentrations of PAI-1 in 163 obese 31 with metabolic syndrome (MS) and 150 lean, healthy women was tested." (PMID 33807923, 2021).
peripheral nerve injury (5 papers, 2017 to 2025). Injury to a peripheral nerve. "Furthermore, research on peripheral nerve injury revealed that TNFRSF1A, BIRC2, and BIRC3 in Schwann cells (SC) assume an anti-apoptotic function by modulating NFκB signaling pathway in response to inflammatory stimuli, thereby mitigating peripheral nerve damage." (PMID 40308566, 2025).
triple-negative breast carcinoma (5 papers, 2016 to 2025). An invasive breast carcinoma which is negative for expression of estrogen receptor (ER), progesterone receptor (PR), and human epidermal growth factor receptor 2 (HER2). "Also in this patient cohort, we observed a significant decrease in TNFRSF1A in both ER-positive and triple-negative breast cancer tissues." (PMID 37041130, 2023).
uveitis (5 papers, 2013 to 2023). An inflammatory process affecting a part of or the entire uvea. "Ocular involvement specifically uveitis was most commonly identified in NLRP3 low-penetrance variants (n = 12; 63%) in comparison to TNFRSF1A- (n = 14; 24%, p = 0.0169) and MEFV variants (n = 6; 18%, p = 0.0141)." (PMID 32563262, 2020).
acute myeloid leukemia (4 papers, 2020 to 2022). Acute myeloid leukemia (AML) is a group of neoplasms arising from precursor cells committed to the myeloid cell-line differentiation. "In THP-1 acute myeloid leukaemia cells, there was a significant decrease in the expression of BCL2, BCLX, and BAD genes and proteins; with a significant increase in TNFR1/TNFRSF1A, CASP-9, and CASP-3 gene expression, when compared to the vehicle control (P ≤ 0.05)." (PMID 35614109, 2022). "Furthermore, the TNFRSF1A expression prolife of various tumors from the GEPIA2 illustrated that TNFRSF1A was significantly overexpressed in four kinds of tumors compared with the corresponding normal samples, including GBM, LAML (acute myeloid leukemia), LGG and PAAD (pancreatic adenocarcinoma)." (PMID 32257943, 2020).
esophageal squamous cell carcinoma (4 papers, 2019 to 2024). Esophageal squamous cell carcinoma (ESCC) is a type of esophageal carcinoma (EC) that can affect any part of the esophagus, but is usually located in the upper or middle third. "For instance, ATXN2 has been shown to enhance the translation of TNFRSF1A by binding to m6A-modified TNFRSF1A mRNA, leading to the activation of NF-κB and MAPK pathways, thereby promoting esophageal squamous cell carcinoma (ESCC) tumorigenesis and progression." (PMID 39039334, 2024).
hyper-IgD syndrome (4 papers, 2013 to 2023). "These are MVK, located on chromosome 12q24, responsible for hyper-IgD syndrome (HIDS), and TNFRSF1A, located on chromosome 12p13.2, responsible for TNF receptor-associated periodic syndrome (TRAPS)." (PMID 23547563, 2013). "Sequencing of the TNFRSF1A and MVK genes revealed no variants associated with Tumor Necrosis Factor Receptor – Associated Periodic Syndrome (TRAPS) or Hyper IgD Syndrome (HIDS), respectively." (PMID 31660995, 2019).
osteosarcoma (4 papers, 2014 to 2022). A usually aggressive malignant bone-forming mesenchymal neoplasm, predominantly affecting adolescents and young adults. "Finally, a 5-gene prognostic model consisting of COL13A1, TNFRSF1A, LILRA6, CTNNBIP1, and CD180 was established for predicting the prognosis of osteosarcoma." (PMID 36035315, 2022).
sarcopenia (4 papers, 2020 to 2025). Progressive decline in muscle mass due to aging which results in decreased functional capacity of muscles. "From the psoas muscle Hi-C dataset we identified unique druggable eGenes (e.g., GRID1, TNFRSF1A, STAT4) which represent potential therapeutic targets for treating the muscle wasting/weakness symptoms associated with NMD and sarcopenia." (PMID 32391060, 2020).
AA amyloidosis (3 papers, 2021 to 2022). Secondary amyloidosis is a form of amyloidosis, that complicates chronic inflammatory disorders (mainly rheumatoid arthritis) and is characterized by the aggregation and deposition of amyloid fibrils composed of serum amyloid A protein, an acute phase reactant. "Hereby, in an adult male with AA amyloidosis and his family members we identified a novel in-frame insertion-type pathogenic variant in one allele of TNFRSF1A gene that caused TRAPS." (PMID 33530412, 2021). "Two genes within those characterizing the affected cats were reported in the literature as related to AA amyloidosis: TREM1 and TNFRSF1A." (PMID 33863921, 2021).
Cachexia (3 papers, 2021 to 2025). Severe weight loss, wasting of muscle, loss of appetite, and general debility related to a chronic disease. "The aim of this study was to assess the relationship between rs767455 (36 T/C) of the TNFRSF1A and the occurrence of nutritional disorders in CHF patients with cachexia." (PMID 33807923, 2021). "The aim of this study was to assess the relationship between SNPs (36T/C) of the TNFRSF1A gene and the occurrence of nutritional disorders in CHF patients with cachexia." (PMID 33807923, 2021). "It is difficult to compare our results to other studies, as there are no available reports regarding the correlation betweenrs767455 (36T/C) of the TNFRSF1A gene and the occurrence of nutritional disorders in CHF patients with cachexia." (PMID 33807923, 2021).
diffuse large B-cell lymphoma (3 papers, 2019 to 2026). "TNFRSF1A expression is reportedly associated with poor prognosis in diffuse large B-cell lymphoma." (PMID 31146704, 2019).
endometrial cancer (3 papers, 2020 to 2025). Primary or metastatic malignant neoplasm involving the endometrium (mucous membrane that lines the endometrial cavity). "Using qRT‐PCR analysis, endometrial cancer tissues (n = 39) exhibited higher expression levels of adiponectin, leptin, IL6, TNFα, and their receptors, IL6R and TNFRSF1A/B, compared to the calibrator sample, which consisted of five pooled benign endometrial control samples." (PMID 40642843, 2025). "The marked upregulation of IL6R and TNF receptors (TNFRSF1A, TNFRSF1B) in cancer tissue compared to controls supports the notion that these cytokines and their signaling pathways are central to the development and aggressiveness of endometrial cancer." (PMID 40642843, 2025).
malnutrition (3 papers, 2022 to 2025). Inadequate nutrition resulting from poor diet, malabsorption, or abnormal nutrient distribution. "In our study, the presence of the TT genotype of the TNFRSF1A gene was related to significantly higher (nearly sixfold) risk of severe malnutrition according to SGA." (PMID 35884467, 2022). "The TT genotype (rs4149570) of the TNFRSF1A gene may be related to a higher risk of nutritional deficiencies (severe malnutrition and CWL) in patients subjected to the IMRT due to HNC." (PMID 35884467, 2022). "Therefore, the aim of this study was to assess TNFRSF1A gene polymorphism (−610 > G, rs4149570) as a predictor of malnutrition or prognostic factor in patients subjected to intensity-modulated radiotherapy (IMRT) due to HNC." (PMID 35884467, 2022). "The significant role of the systemic inflammatory response mediated by the activation of TNFR1 in the etiopathology of cancer-related malnutrition (CRM) encourages the investigation of the single-nucleotide polymorphisms (SNPs) of the TNFRSF1A gene as risk factors for nutritional deficiencies." (PMID 35884467, 2022). "In turn, independent predictors of a higher risk of severe malnutrition included stage IV disease according to TNM (OR = 2.69; p = 0.0107), excessive alcohol consumption (OR = 3.99, p = 0.0174), and TT genotype of TNFRSF1A gene (OR = 5.05, p = 0.0350)." (PMID 35884467, 2022). "In the case of survival, apart from the classic prognostic factors such as T4 stage, advanced stage of disease (IV), and the presence of moderate or severe malnutrition, the occurrence of CWL and the TT genotype of the TNFRSF1A gene were significantly related to a higher risk of death." (PMID 35884467, 2022).
myocarditis (3 papers, 2020 to 2024). Myocarditis is a condition that is characterized by inflammation of the heart muscle (myocardium). "Furthermore, Tnfrsf1a−/− mice were completely protected from the development of myocarditis induced by immunization with cardiac myosin or by an adoptive transfer of autoreactive T lymphocytes." (PMID 33053859, 2020).
non-small cell lung carcinoma (3 papers, 2008 to 2024). A group of at least three distinct histological types of lung cancer, including non-small cell squamous cell carcinoma, adenocarcinoma, and large cell carcinoma. "The TNFRSF1A gene plays a crucial role in non-small cell lung cancer growth, invasion, and metastasis." (PMID 35899106, 2022).
pericarditis (3 papers, 2019 to 2025). An inflammatory process affecting the pericardium. "Eleven variants were located in genes already associated with recurrent pericarditis (NLRP3, TNFRSF1A and MEFV) and five in inflammation/immunodeficiency-related genes (IFIH1, NFKBIA, JAK1, NOD2 and ALPK1)." (PMID 39347728, 2024). "Interestingly a single variant in the TNFRSF1A gene (NM_001065.4:c.362G>A) has been found in seven patients of our series (P = 0.0003), suggesting that it might be a possible predisposing factor for recurrent pericarditis." (PMID 39347728, 2024).
Tinnitus (3 papers, 2021 to 2024). Tinnitus is an auditory perception that can be described as the experience of sound, in the ear or in the head, in the absence of external acoustic stimulation. "Genome-wide association studies have identified and replicated two common variants in the Chinese population (rs2846071; rs4149577) in the intron of TNFRSF1A, associated with noise-induced tinnitus." (PMID 38334885, 2024). "Colocalization analysis further showed that the tinnitus-associated SNP rs4149577 is colocalized with eQTL signals for TNFRSF1A in brain tissues (PP0 = 0.040, PP1 = 0.002, PP2 = 0.613, PP3 = 0.057, PP4 = 0.288)." (PMID 34482816, 2021). "Further analysis was needed in a larger sample size study to confirm the genetic associations of WNT11 and TNFRSF1A with tinnitus." (PMID 34482816, 2021). "Together, these pieces of evidence suggested a potential role for TNFRSF1A in the development of tinnitus." (PMID 34482816, 2021). "Intriguingly, the newly identified significantly associated genes WNT11 and TNFRSF1A were just in the Wnt and TNF pathways, respectively, therefore highlight the critical roles of these two pathways in the development of tinnitus." (PMID 34482816, 2021). "Together, these pieces of evidence suggested potential roles for WNT11 and TNFRSF1A in the development of tinnitus." (PMID 34482816, 2021). "Here, our eQTL analyses showed that the genotypes of rs2846071 or rs4149577 are correlated with the expression levels of WNT11 or TNFRSF1A, respectively, in multiple brain tissues, suggesting that these two genes may be the candidate genes of tinnitus." (PMID 34482816, 2021).
TRAP syndrome (3 papers, 2019 to 2024). "In the present case, genetic testing revealed a heterozygous R92Q mutation in the TNFRSF1A gene, confirming the diagnosis of TRAPS syndrome." (PMID 39001227, 2024). "Mutations in the TNFRSF1A gene are dominantly inherited in TRAP syndrome (TRAPS), signifying the association of TNFRSF1A to auto-inflammatory diseases." (PMID 31824568, 2019). "The TNF receptor-associated periodic syndrome (TRAPS), first named Familial Hibernian Fever (FHF), is an autosomal dominant disease caused by heterozygous, usually missense, mutations in the TNFRSF1A gene with poor genotype-phenotype." (PMID 39618694, 2024).
adenoma (2 papers, 2023 to 2026). A neoplasm arising from the epithelium. "In summary, CD8+ Tex cells may activate RUNX2 in malignant EPCs through TNF-α binding to TNFRSF1A, promoting the adenoma-to-carcinoma transition and contributing to poor prognosis." (PMID 42056097, 2026). "Conversely, TNFRSF1A inhibitor Atrosab downregulated RUNX2 expression and partially reversed RUNX2 overexpression-induced adenoma-to-adenocarcinoma transition." (PMID 42056097, 2026).
age-related macular degeneration (2 papers, 2024 to 2025). Age-related loss of vision in the central portion of the retina (macula), secondary to retinal degeneration. "In conclusion, identifying genetic variations in ARMS2, VEGFA, TNFRSF1A, TNFRSF1B, and IL1B1 provides valuable insights into the susceptibility to and treatment outcomes for age-related macular degeneration." (PMID 39273697, 2024). "In published databases, we did not uncover any studies examining the serum correlations of TNFRSF1A, TNFRSF1B, and IL1B1 with age-related macular degeneration." (PMID 39273697, 2024).
autoimmune lymphoproliferative syndrome (2 papers, 2016 to 2017). Autoimmune lymphoproliferative syndrome (ALPS) is a rare, inherited disorder characterized by non-malignant lymphoproliferation, multilineage cytopenias, and a lifelong increased risk of Hodgkin's and non-Hodgkin's lymphoma. "Mendelian syndromes such as autoimmune lymphoproliferative syndrome (ALPS) and TNF receptor associated periodic syndrome (TRAPS) are caused by mutations in FAS (or other members of the FAS signalling pathway) and TNFRSF1A, respectively." (PMID 27435189, 2016).
Hyponatremia (2 papers, 2021 to 2023). An abnormally decreased sodium concentration in the blood. "Hyponatremia was usually more frequent in LGI1 encephalitis patients with lower serum TNFRSF1A levels (p < 0.05)." (PMID 37644514, 2023).
mucositis (2 papers, 2018 to 2024). Mucositis is inflammation and damage of the mucous membranes lining the mouth and other parts of the gastrointestinal (GI) tract. "Based on the study results we found that studied SNP of TNFRSF1A had significant effect on the severity of acute radiation-induced mucositis toxicity." (PMID 28401452, 2018).
Myalgia (2 papers, 2017 to 2020). "Patients w/o MS and with TNFRSF1A variants showed significant more often myalgias (n = 7; 88%) compared to patients with MEFV variants (n = 7; 37%, p = 0.0169)." (PMID 32563262, 2020).
nutritional disorder (2 papers, 2021 to 2022). Any condition related to a disturbance between proper intake and utilization of nourishment. "The aim of the study was to assess the relationship between a functional single-nucleotide polymorphism (SNP) −610 T > G (rs4149570) of the TNFRSF1A gene and the occurrence of nutritional disorders in patients subjected to RT due to HNC." (PMID 35884467, 2022). "Multivariable analysis revealed that the TT genotype of the TNFRSF1A gene (−610 T > G) was independently correlated with a higher risk of nutritional disorders." (PMID 35884467, 2022). "Despite these limitations, to our knowledge, this is the first study attempting at an assessment of the TNFRSF1A:rs767455 genotype, demonstrating that it may be a useful marker in determining the risk of nutritional disorders in patients with CHF." (PMID 33807923, 2021). "It should be noted that the available literature lacks studies directly related to the relationship between TNFRSF1A gene status and nutritional disorders." (PMID 33807923, 2021). "It should be noted that, until now, polymorphism −610 T > G (rs4149570) of the TNFRSF1A gene was not studied in relation to the risk of nutritional disorders or as a prognostic factor in patients subjected to IMRT due to HNC." (PMID 35884467, 2022).
oral mucositis (2 papers, 2018 to 2022). Inflammation of the mucous membranes of any of the structures in the mouth. "The polymorphism of TNFRSF1A is regarded as a predictive factor for RT-induced oral mucositis." (PMID 35453806, 2022).
spondyloarthritis (2 papers, 2015 to 2018). "We investigated whether polymorphisms (SNPs) in the promoter region of TNFA, or in the autoinflammatory TNFRSF1A and MEFV genes, concur with HLA-B27 in enhancing the risk of Spondyloarthritis (SpA) and/or in predicting the response to anti-TNFα treatment." (PMID 29579081, 2018).
astrocytoma (1 paper, 2020). "On the other hand, TNFRSF1A expression increased in the order of control (normal brain) tissues, oligodendroglioma, astrocytoma, and GBM." (PMID 32257943, 2020).
bronchopneumonia (1 paper, 2015). Acute inflammation of the walls of the terminal bronchioles that spreads into the peribronchial alveoli and alveolar ducts. "Sequencing of the TNFRSF1A gene was performed in this patient after about 18 years of recurrent episodes of bronchopneumonia, fever and other systemic signs of inflammation with an incomplete response to steroid treatment." (PMID 25888769, 2015).
conjunctivitis (1 paper, 2023). Inflammation of the conjunctiva of the eye. "TNFRSF1A variants can result in TNF receptor-associated periodic syndrome (TRAPS), an autoinflammatory disease characterized by paroxysmal fever, pain (chest, abdomen, muscles), rash and outwards signs of inflammation (e.g., conjunctivitis, periorbital edema)." (PMID 37234784, 2023).
Fever (1 paper, 2019). Body temperature elevated above the normal range. "Altogether, the patient history is more immediately related to a potential PLCG2 defect than to autoinflammatory periodic fever associated to abnormal function of TNFRSF1A." (PMID 32047491, 2019).
Headache syndromes (1 paper, 2020). "Headache syndromes were frequently observed among all AID subgroups w/o MS and most commonly found in patients with MEFV- (n = 14; 74%) followed by TNFRSF1A- (n = 5; 63%) and NLRP3 low-penetrance variants (n = 10, 59%)." (PMID 32563262, 2020).
Impaired glucose tolerance (1 paper, 2024). An abnormal resistance to glucose, i.e., a reduction in the ability to maintain glucose levels in the blood stream within normal limits following oral or intravenous administration of glucose. "This elevation suggested systemic atherosclerosis linked to impaired glucose tolerance.S1–3 On the other hand, serum expression of TNFRSF1A, CXCL4, MIP‐1 γ, MMP‐3, VEGFR2, IGF‐1, HGFR, OPN, and OPG was significantly lower in db/db mice." (PMID 39001701, 2024).
leiomyoma (1 paper, 2021). A well-circumscribed benign smooth muscle neoplasm characterized by the presence of spindle cells with cigar-shaped nuclei, interlacing fascicles, and a whorled pattern. "A total of eight leiomyoma-related DEGs (EGR1, CEBPB, IL6, PECAM1, VWF, TNFRSF1A, CD34 and ACE) were found upregulated in MF versus M only." (PMID 33807176, 2021).
lymph node metastasis (1 paper, 2014).
medulloblastoma (1 paper, 2025). A malignant, invasive embryonal neoplasm arising from the cerebellum. "All immune cells express receptors for TNF-alpha (TNFRSF1A and TNFRSF1B) and IFN alpha (IFNAR1 and IFNAR2) and are enriched for these pathways, indicating that all these immune cell types are primed to respond to secreted TNF-alpha and IFN alpha in the medulloblastoma TME." (PMID 40240536, 2025).
peripheral T-cell lymphoma (1 paper, 2024). "The TNF receptor superfamily member 1B (TNFRSF1B), TNFRSF1A linked by the death domain TRADD, and TRAF1 associated with TNF receptors are inhibited in peripheral T-cell lymphoma when chemotherapy resistance occurs." (PMID 38468267, 2024).
Renal amyloidosis (1 paper, 2011). A form of amyloidosis that affects the kidney. "Nine (82%) of the 11 children carrying TNFRSF1A structural mutations had a family history consistent with an autoinflammatory disease (including renal amyloidosis in 3 families), for a total of 24 affected individuals." (PMID 21225694, 2011).